DUS1L (dihydrouridine synthase 1 like)
Description:
Catalyzes the synthesis of dihydrouridine, a modified base found in the D-loop of most tRNAs. Specifically modifies U16 and U17 in cytoplasmic tRNAs. Affects the level of some mature tRNA and thereby the total cellular translation.
Synonyms: DUS1; PP3111
Tractability: Antibody: the Human Protein Atlas places it where antibodies can reach. PROTAC: ubiquitination databases record sites on it; its protein half-life has been measured.
Gene: Protein-coding gene on chromosome 17 (82,057,506 to 82,066,206, reverse strand). Ensembl gene ENSG00000169718.
Subcellular location: Cytoplasm; Nucleus
Subcellular location (Human Protein Atlas): Plasma membrane
Gene Ontology:
Molecular function: protein binding; tRNA-dihydrouridine16 synthase activity; tRNA-dihydrouridine17 synthase activity; tRNA dihydrouridine synthase activity; flavin adenine dinucleotide binding
Biological process: tRNA dihydrouridine synthesis; tRNA processing
Cellular component: cytoplasm; nucleus
Genetic constraint (gnomAD): Loss-of-function variants: 50 observed, 57.4 expected, observed/expected ratio (o/e) 0.87, 90% interval 0.69 to 1.1. The upper end of that interval is the gene's LOEUF score, 1.1, which puts it in group 4 of 6, group 1 being the genes least tolerant of losing a copy. Missense variants: 526 observed, 558.68 expected, observed/expected ratio (o/e) 0.94, 90% interval 0.88 to 1.01. Synonymous variants: 239 observed, 227.95 expected, observed/expected ratio (o/e) 1.05, 90% interval 0.94 to 1.17.
Homologues: Orthologues: pig DUS1L (92% identical), mouse Dus1l (91% identical), rat Dus1l (90% identical), guinea pig DUS1L (90% identical), macaque DUS1L (87% identical), dog DUS1L (81% identical), tropical clawed frog dus1l (78% identical), zebrafish dus1l (71% identical), Drosophila melanogaster Dus1 (51% identical), Caenorhabditis elegans F36A2.2 (39% identical). Paralogues in human: DUS4L (23% identical), DUS2 (22% identical), DUS3L (19% identical).
Diseases named in the same sentence as DUS1L in open-access papers:
DUS1L is named in the same sentence as 5 diseases in open-access papers, as found by Europe PMC text mining. Sharing a sentence is not in itself a finding about the gene and the disease. The quoted sentences say what the papers report.
breast carcinoma (1 paper, 2021). "For example, DUS1L, a gene negatively correlated with CD274, was shown in ovarian, gastric, and breast cancer to be beneficial at high levels of expression." (PMID 34067485, 2021).
glioblastoma (1 paper, 2024). The most malignant astrocytic tumor (WHO grade IV). "DUS1L knockout in the glioblastoma cell lines LNZ308 and U87 causes loss of D16/D17." (PMID 39354220, 2024). "DUS1L overexpression changes the amount of several D16/D17-containing tRNAs and increases total cellular translation and cell growth in glioblastoma cells." (PMID 39354220, 2024). "DUS1L supported growth of a glioblastoma (WHO grade IV) cell line, and higher DUS1L expression was associated with poorer prognosis in glioma patients." (PMID 39354220, 2024). "Therefore, DUS1L supports growth of a glioblastoma cell line under a cultured condition." (PMID 39354220, 2024).
glioma (1 paper, 2024). A benign or malignant brain and spinal cord tumor that arises from glial cells (astrocytes, oligodendrocytes, ependymal cells). "A Kaplan–Meier plot showed that increased expression of DUS1L was associated with poorer prognosis of glioma patients." (PMID 39354220, 2024). "In addition, higher DUS1L expression was associated with poorer prognosis of glioma patients and DUS1L affected the growth rates of the selected cancer cell line." (PMID 39354220, 2024). "Moreover, higher DUS1L expression in glioma patients is associated with poorer prognosis." (PMID 39354220, 2024).
cancer (4 papers, 2014 to 2025). A tumor composed of atypical neoplastic, often pleomorphic cells that invade other tissues. "Further investigations are required to determine whether increased DUS1L expression in cancer tissues, which is likely lower than the expression level achieved in vector-mediated DUS1L OE cells, changes the proteome of cancer cells." (PMID 39354220, 2024). "Based on the transcriptomic data of TCGA pan-cancer cohorts, the expression of RRP1B, RRP1, MAZ, DUS1L, and HGH1 was identified to correlate positively with the expression of SLC19A1 in 40 types of cancers." (PMID 40149548, 2025).
DUS1L also shares sentences with these, for which no sentence is quoted: COVID-19 (1 paper).